LEP (leptin)
Diseases named in the same sentence as LEP in open-access papers (continued):
Sharing a sentence is not in itself a finding about the gene and the disease.
Obesity (continued). "Baseline leptin and adiponectin levels reflect the metabolic conditions at the time and are determined by nutritional status and correlate to the amount of fat mass, where leptin increase and adiponectin decrease with increasing obesity." (PMID 28919840, 2017). "Specifically natural killer (NK) cells seem to be functionally altered by obesity-induced high elevated leptin levels." (PMID 28690853, 2017). "As the hypothalamus mediates the anti-obesity actions of leptin, one of the models proposed a decrease in leptin transport across the BBB." (PMID 28321206, 2017). "From these variables, obesity presents a unique importance while evaluating serum leptin levels because of the fact that obese subjects have higher serum leptin values, which correlates body weight percentage, than normal weight subjects." (PMID 28890432, 2017). "Analyses of body fat, plasma hormone levels, and visceral white adipose tissue DNA methylome and transcriptome collectively indicate that the F4 obesity is consistent with a leptin resistant, thrifty phenotype." (PMID 29222412, 2017). "Protein tyrosine phosphatase 1B (PTP1B) and α-glucosidase are important targets to treat obesity and diabetes, due to their deep correlation with insulin and leptin signalling, and glucose regulation." (PMID 28933230, 2017). "Leptin, which is secreted by adipocytes, is increased under conditions of obesity and has been shown to enhance ERα expression in both normal epithelial cells and breast cancer cell lines." (PMID 29187227, 2017). "Current studies showed that the potential mechanisms of obesity-promoting gonadal axis initiation mainly related to insulin resistance and hyperinsulinemia, hyperandrogens, and leptin." (PMID 29064384, 2017). "In particular, inhibition of JNK activity appears to be effective in preventing or diminishing the development of obesity and ameliorating leptin resistance under high-fat diet feeding condition." (PMID 28165482, 2017). "Other related obesity biomarkers including plasma lipid profiles, insulin, leptin, ghrelin and adiponectin levels also showed significant improvement (p < 0.05)." (PMID 28228098, 2017). "Leptin transport into the brain is modulated by conditions including obesity and fasting, as well as metabolic factors." (PMID 28377744, 2017). "Obesity induced by hfd is characterized by increased circulating levels of the adipocyte-derived hormone leptin, which can increase sympathetic nerve activity and raise blood pressure through up-regulation of central RAS and pro-inflammatory cytokines." (PMID 29170528, 2017). "As an obesity-related adipokine, the serum level of leptin was decreased by exercise training (p = 0.022), whereas leptin levels remained unchanged in the control group." (PMID 28178355, 2017). "A majority of obesity-related autonomic, behavioral, metabolic, and neuroendocrine responses in rodents and humans are mitigated or restored by leptin “replacement”." (PMID 28107353, 2017). "Many others studies have noticed the function of LAR as a good marker of obesity, diabetes mellitus, insulin resistance and metabolic syndrome compared to adiponectin or leptin alone." (PMID 28878827, 2017). "Irisin is increased in obesity in a manner similar to leptin, which suggests that irisin resistance develops similarly to that of leptin." (PMID 28077341, 2017). "This was mainly due to the fact that patients with fibromyalgia and overweight/obesity showed lower leptin levels compared with the participants in the control group with overweight/obesity." (PMID 28226002, 2017). "It has been reported that obesity and overnutrition modified the central leptin sensitivity and appetite-controlling signals." (PMID 28881823, 2017). "This suggests that patients with fibromyalgia and overweight/obesity produce more leptin than those with fibromyalgia and normal weight." (PMID 28226002, 2017).
Obesity (continued). "Further, a recent study showed that WT mice with diet-induced obesity retain sensitivity to the central anorexigenic actions of endogenous leptin and gain weight when treated with a leptin receptor antagonist, unlike genetically-obese mice." (PMID 28427343, 2017). "Opposite results were obtained by Pehlivanov and Mitkov, who showed a positive correlation between serum leptin levels and insulin resistance, independently of obesity." (PMID 27473078, 2017). "Taken together, the facts presented above seems to indicate that it is possible that both factors can affect plasma leptin concentration separately, but coexistence of obesity and low 25(OH)D3 concentration intensify this effect." (PMID 29295491, 2017). "Leptin- and resistin-exhibited elevated levels are positively correlated with obesity and its complications." (PMID 29142618, 2017). "When fed HF/HSD, Ptprj-KO mice also gradually got obese due to a decrease in leptin sensitivity as judged by the activation of STAT3, but they exhibited attenuated development of leptin resistance with obesity." (PMID 28912580, 2017). "Mice hypomorphic for RPGRP1L exhibit hyperphagic obesity as the result of diminished leptin sensitivity in ObRb-expressing neurons." (PMID 28270795, 2017). "The coexistence of an increasing of the body fat content and obesity in animal models and humans correlates with higher levels of leptin; this is widely interpreted as evidence of “leptin resistance”." (PMID 28490838, 2017). "Typical obesity in humans is commonly associated with elevation in leptin levels and decrease in adiponectin levels, suggesting that there must have been existed the imbalance of leptin-adiponectin regulation and this imbalance may play a role in the development of obesity related complications." (PMID 29020116, 2017). "Unadjusted leptin levels were lower in fibromyalgia patients than controls, a finding that was more remarkable in fibromyalgia patients with overweight/obesity." (PMID 28226002, 2017). "The example we wish to highlight is the trans-pQTL for leptin, one of the most studied proteins in obesity." (PMID 29234017, 2017). "Monogenic obesity stemming from leptin/melanocortin pathway abnormalities should be considered in differential diagnosis of early onset obesity." (PMID 29280743, 2017). "This study suggests that obesity enhances the cross-talk between chondrocytes and synovial fibroblasts via raised levels of the pro-inflammatory adipokine leptin, leading to greater production of IL-6 in OA patients." (PMID 28615667, 2017). "The resistance to HFD-induced obesity in ATGLi mice was accompanied by a 90% decrease and 16% increase in plasma concentrations of leptin and adiponectin, respectively." (PMID 28327588, 2017). "Routinely used rodent models for obesity and diabetes research have a monogenic defect in leptin signaling that initiates obesity." (PMID 28640857, 2017). "Individuals with obesity display markedly increased circulating leptin levels and decreased adiponectin levels, which suggests leptin resistance and adiponectin deficiency." (PMID 29020116, 2017). "Understanding the sexual dimorphism in leptin levels is important as it relates to the clinical implications of obesity." (PMID 28811502, 2017). "Methylation levels of leptin promoter are negatively associated with leptin production, suggesting that our demonstration of increased leptin promoter methylation level may be responsible for the defect of leptin production and thus be implicated in the programming of obesity by CAP exposure." (PMID 28645299, 2017). "We reported here the first evidence that megalin blockage in BBB endothelial cells reduce the brain leptin uptake leading to hyperphagia and obesity." (PMID 28143489, 2017). "IPA analysis did not indicate a significant overlap of genes in the canonical pathways of which Leptin is a component, including Leptin signaling in obesity, insulin, or Jak/Stat." (PMID 28192065, 2017).
Obesity (continued). "In such a context, the characterization of the unidentified neurons capable of modulating POMC/CART neurons in response to leptin can be seen as major challenge of the current research in the neurobiology of obesity." (PMID 28690493, 2017). "Mounting evidence in rodent and cell-culture models indicate that it is an anti-diabetic, anti-obesity and anti-cancer agent with potent anti-oxidative, anti-inflammatory, anti-proliferative, apoptosis-inducing and leptin-sensitizing properties." (PMID 29165314, 2017). "Mutations in the leptin gene (LEP) can alter the secretion or interaction of leptin with its receptor, leading to extreme early-onset obesity." (PMID 29101506, 2017). "In patients with obesity, circulating leptin levels are significantly higher than in normal age- and sex-matched patients, suggesting that a level of leptin resistance exists in these obese patients." (PMID 27379019, 2016). "Since leptin resistance mainly occurs in obesity, it is worth mentioning that some studies found obesity to be significantly increased in meningioma patients." (PMID 26894859, 2016). "Despite these shortcomings our study is one the very few to report on the relationship of leptin and adiponectin with lipid profile, anthropomorphic indexes of obesity and insulin sensitivity among subjects of African ancestry." (PMID 27189377, 2016). "In this regard, PTP1B knockout mice increases sensitivity to leptin and insulin, and are resistant to a high-fat diet-induced obesity." (PMID 27812350, 2016). "In conclusion, this study demonstrated that maternal plasma leptin levels during and after pregnancy differed significantly between the women with obesity and morbid obesity." (PMID 27257506, 2016). "To test the contribution of obesity to leptin resistance in LRbCre/Bbs1fl/fl mice, we performed several experiments." (PMID 26926121, 2016). "Leptin uptake and insulin secretion were found controlled by miR-200a, miR-200b, and miR-429, which are related to obesity." (PMID 27147943, 2016). "We classify this network into 5 modules and identify new links between the recently discovered fat mass and obesity associated FTO gene with well studied examples such as insulin and leptin." (PMID 26886906, 2016). "LEP has been directly associated with obesity, while ADIPOQ has been inversely associated with obesity and visceral fat accumulation." (PMID 27857161, 2016). "We tested the effects of leptin, produced in the physiological adipocyte location, on metabolism in mouse models of genetic and dietary obesity." (PMID 27055280, 2016). "The animals were fed with Purina Diet ad libitum and showed obesity at 1 month of age, hyperinsulinemia and hyperglycemia at 18 weeks of age, increased leptin levels at 17–18 weeks of age, as well as increased cholesterol levels at 14 weeks of age." (PMID 27708685, 2016). "This strategy prevented the development of obesity in the LRbCre/Bbs1fl/fl mice as indicated by the normalization of plasma leptin levels (3.0±0.3 ng/mL in calorie restricted LRbCre/Bbs1fl/fl mice vs. 3.1±0.5 ng/mL in control mice)." (PMID 26926121, 2016). "Circulating leptin is actually elevated in obesity, but hypothalamic leptin resistance aggravates obesity through inhibition of appetite control and lipid oxidation." (PMID 27148161, 2016). "Human obesity is due to a complex interaction among environmental, behavioral, developmental and genetic factors, including the interaction of leptin (LEP) and leptin receptor (LEPR)." (PMID 28096764, 2016). "Taken together, our results reveal new links between obesity and cartilage damage that are induced by leptin-mediated effects on cell behaviour, senescence and intracellular signalling." (PMID 27077804, 2016). "Results in this study add knowledge on this issue by showing a significant difference in leptin levels between the three degrees of obesity." (PMID 27257506, 2016).
Obesity (continued). "Leptin, serving as an anti-obesity hormone by binding to leptin receptor, is secreted by mature adipocytes in proportion with the size of fat depots." (PMID 27708685, 2016). "Among several neuromodulators involved in activation of the SNS, one of the most studied in obesity is leptin, an adipokine secreted by adipocytes proportionally to the degree of adiposity." (PMID 27273815, 2016). "An advanced understanding of the physiological and pathophysiological actions of leptin and insulin in the CNS will shed light on potential therapeutic interventions for obesity." (PMID 27812350, 2016). "Leptin resistance is observed in mice with high-fat-diet-induced obesity and many other mouse obesity models." (PMID 26818770, 2016). "We further generated and characterized mice mutant in both leptin and FADD by introducing the FADD‐D allele into the leptin‐deficient (ob/ob) mice to investigate the genetic influence of FADD in obesity." (PMID 27357657, 2016). "The molecular mechanisms responsible for leptin resistance and possible pharmacological treatments for obesity have been discussed herein, with a focus on ER stress." (PMID 27375555, 2016). "The recent identification of the ob gene (obesity) and its product leptin and the db gene, whose product is the leptin receptor, provides important elements of a molecular basis for this physiologic concept." (PMID 26787421, 2016). "A previous study showed a decrease in the ratio of leptin levels in cerebrospinal fluid versus serum with obesity, suggesting that the capacity for leptin transport is lower in obese patients." (PMID 27375555, 2016). "We also examined plasma concentrations of leptin, which has postulated roles in obesity and insulin action." (PMID 27134637, 2016). "Levels of leptin are elevated in the circulation of adults with obesity, metabolic syndrome, and cardiovascular disease." (PMID 27135745, 2016). "Third, some studies have reported higher leptin levels among lean individuals with abdominal obesity compared with those with overall obesity." (PMID 27294726, 2016). "For instance, people with low birth weight present with higher plasma leptin concentrations than would be expected from their degree of obesity." (PMID 27141948, 2016). "This study aimed to explore the potential relationship of leptin and adiponectin, with obesity, plasma lipids and insulin resistance in a Cameroonian population." (PMID 27189377, 2016). "High circulating leptin levels and attenuated anorexic responses to exogenous leptin suggest that leptin resistance plays a role in obesity." (PMID 26849804, 2016). "Here we show that treatment with encapsulated leptin-producing adipocytes improves glucose tolerance in genetic and diet-induced mouse models of obesity." (PMID 27055280, 2016). "Because leptin has an anti-obesity effect, the hormone was initially expected to decrease body weight in obese patients." (PMID 27746736, 2016). "Here, we showed that mice lacking IRE1α specifically in POMC neurons (PIKO) are lean and resistant to high-fat diet-induced obesity and obesity-related insulin resistance, liver steatosis and leptin resistance." (PMID 27558934, 2016). "These appetite-related factors (i.e. ghrelin, leptin, AgRP and neuropeptide Y) have been reported to moderate overeating/obesity, affecting the anticipation, consumption, and acquisition of food." (PMID 26754043, 2016). "Since leptin circulates at levels proportional to body fat, obesity results in an increase in plasma leptin concentration." (PMID 27655337, 2016). "Although both leptin and adiponectin are secreted from adipose tissue, the two adipokines behave differently in high-fat diet-induced obesity." (PMID 27528227, 2016). "In obesity, a decreased sensitivity to leptin occurred, resulting in an inability to detect satiety despite the accumulation of high energy." (PMID 27123038, 2016).
Obesity (continued). "An obesity-related environment, such as leptin-treatment or adipocyte-conditioned medium (Ad-CM), promoted 4T1 cell proliferation and metastasis." (PMID 27983683, 2016). "This enzyme was previously identified as a priority drug target, as DGAT1 mutant mice are viable and show numerous beneficial metabolic characteristics such as resistance to diet-induced obesity and increased insulin or leptin sensitivity." (PMID 27428418, 2016). "This diet has been employed as an obesity induction model in rats and mice and has been accompanied by increased body weight, adiposity, levels of leptin, and plasma concentrations of cholesterol, glucose, and insulin." (PMID 28018521, 2016). "Since a mutation in the Ob-Rb receptor in db/db mice results in severe obesity, the Ob-Rb receptor is considered to play an important role in the anti-obesity effects of leptin." (PMID 27375555, 2016). "The findings also point to impairment in leptin signaling due to mishandling of the LRb as a major mechanism for energy imbalance leading to obesity in BBS." (PMID 26926121, 2016). "As energy storage capacity in adipocytes is exceeded during the period between the onset of overweight/obesity and the start of the MS, leptin resistance develops." (PMID 27445827, 2016). "The interest in LEP and LEPR as susceptibility genes for human obesity led to the identification of several common polymorphisms, among which LEPR –2548 G/A and LEPR Gln223Arg are of major importance." (PMID 27015185, 2016). "This points to dysregulation of the leptin-SOCS-3 axis, especially in obese individuals, and to a possible obesity-related pathogenic mechanism in OA." (PMID 27716333, 2016). "In diet-induced obesity, running activity decreases the expression of mRNA for leptin in both visceral adipose tissue and WAT." (PMID 27268060, 2016). "Our observations need to be reproduced in other cancer cell systems, but the present study provides additional assurance of safety of OB3 over leptin as a potential anti-obesity pharmaceutical." (PMID 27050378, 2016). "Genetic and pharmacological manipulations of hypothalamic HDAC5 activity had profound effects on food intake and body-weight control in our studies and overall suggest a beneficial role for selected HDAC5 activation against leptin resistance and obesity." (PMID 26923837, 2016). "We previously reported that postnatal deletion of SF-1 in the VMH leads to high fat diet induced obesity due to impaired thermogenesis and blunted leptin signaling." (PMID 27598259, 2016). "In obesity, circulating concentrations of anti-inflammatory adipokines are lower (i.e. adiponectin) and pro-inflammatory adipokines (i.e. leptin) are elevated compared with lean individuals." (PMID 27023786, 2016). "Further study is required to clarify the regulatory mechanisms of obesity and leptin levels in metabolic syndrome models." (PMID 27322312, 2016). "QTLs related to complex obesity-related traits such as body weight, glucose and leptin levels were found to overlap within the Acss2 genomic region." (PMID 27483348, 2016). "In leptin-deficient mice, the downstream targets (NPY/AGRP neurons) are therefore constitutively active promoting hyperphagia and resulting in obesity." (PMID 26819774, 2016). "Leptin, an important regulator of mass of adipose tissue is found to be downregulated in obesity and psoriasis." (PMID 26966903, 2016). "The purpose of this study was to investigate the effects of hypoxic living and exercise training on obesity and adipose tissue leptin/leptin receptor in dietary-induced obese rats." (PMID 27932989, 2016). "Obesity enhances the leptin level by increasing adiposity and up-regulating enzyme expression, including β-oxidation and mitochondrial uncoupling, to dissipate the excess of energy." (PMID 27618865, 2016). "In the context of obesity, low grade inflammation has been suggested to contribute to the development of insulin and leptin resistance." (PMID 27410967, 2016).